CD44 (CD44 molecule (IN blood group))
Diseases named in the same sentence as CD44 in open-access papers (continued):
Sharing a sentence is not in itself a finding about the gene and the disease.
tumor (continued). "CD44 knockdown by CD44 siRNA decreased the total number and size of tumor spheres stimulated by rhHMGB1." (PMID 33661757, 2021). "Inoculation with 102 or 103 ALDH+CD44+CXCR4+CD24+-PCa cells produced the greatest tumour mass within the shortest time, as compared with three other sorted subpopulations." (PMID 34247196, 2021). "In contrast, in the derived tumor cell lines, the levels of meDNA were increased at several locations inside the body of the CD44 gene as determined by MeDIP." (PMID 34086943, 2021). "This indicated the enhanced tumour-initiation abilities of ALDH+CD44+CXCR4+CD24+- PCa cells in vitro, under androgen-deprived conditions in vitro." (PMID 34247196, 2021). "CD44 promotes tumor resistance to ROS- and chemotherapy-induced stress by regulating some of the transcription coactivators of the tumor suppressor Hippo signaling pathway that consists of a cascade of conserved kinases and transcription coactivators." (PMID 33505471, 2021). "CD44+/CD24− population is considered as the tumorigenic (tumor initiating) cells or CSCs in breast cancer." (PMID 33731668, 2021). "Treatment of the mice with the CD44 neutralizing antibody significantly suppressed tumor growth and alleviated bone damage, suggesting a possible option for adjuvant therapy of GCTB in addition to currently used bisphosphonates and Denosumab." (PMID 34556636, 2021). "Previous studies demonstrated that CD44 is a receptor for HA expressed in highly metastatic tumor cells." (PMID 34770956, 2021). "As intravenous leiomyomatosis is a disease in which tumors grow in veins, presumably, CD44-positive mesenchymal tumor stem-like cells have the capacity for intravascular infiltration." (PMID 34563053, 2021). "In a study with MDA-MB-231 cells, PLGA NPs loaded with PTX and SLM and coated with hyaluronic acid (HLA) showed a high binding efficiency against CD44+ cells and cytotoxicity against both bulk tumor cells and CSCs." (PMID 34361141, 2021). "The specific binding between HA and its derivatives and CD44 can be used to target the delivery of anti-tumor drugs to tumor cells with high CD44 expression." (PMID 34452196, 2021). "In the primary tumor tissue, staining for CD44 occurred in the cytoplasm of HNSCC cells and immune cells." (PMID 34287293, 2021). "In contrast, Abs directed against the constant domain of CD44 is likely to target other tissues such as splenic leukocytes in addition to tumor cells." (PMID 33594192, 2021). "Accumulated hyaluronic acid shed by tumor cells subsequently mediates adhesion to the endothelium via the glycoprotein CD44." (PMID 33637851, 2021). "With regard to tumor stage, CD44 was more frequently expressed in stage III (68.06 ± 8.09, p < 0.0001) and stage II (61.96 ± 7.25, p = 0.002) than stage I (50.95 ± 3.66), leading to a significant difference between stage II and III(p = 0.018)." (PMID 34837915, 2021). "Here CD44 antibody-conjugated SWCNTs had a very significant role in selective active targeting of CSCs, which improved the therapeutic efficiency of this tumor therapy." (PMID 35431911, 2021). "Blockade of IL-6 with tocilizumab and STAT3 knockdown attenuated CD44+ sphere formation and tumor growth of patient-derived HCC as well as breast xenografts." (PMID 34235155, 2021). "In this study, we identified CD44 as a binding partner of Eno1 and observed CD44-mediated inhibition of Eno1's anti-tumor action." (PMID 34373756, 2021). "Blocking STAT3 activation by a specific inhibitor effectively blocked the tumor spheroid formation and decreased the number of CD44+ ALDH+ cells, and further induced apoptosis in HNSCC, this was consistent with our study." (PMID 34502158, 2021). "CD24- CD44+ BCSCs are localized at the tumor invasive edge, staying quiescent with highly invasive characteristics while ALDH+ BCSCs are located at the center of tumor with highly proliferative characteristics." (PMID 34801088, 2021).
tumor (continued). "By contrast, introduction of miR-34a antagomirs in CD44– PCa cells promoted tumor regeneration and metastasis." (PMID 33763422, 2021). "In the present report, we elucidate the mechanism by which CD44 is cleaved, and show that this occurs at an increased rate in stem-like tumor cells grown in spheres." (PMID 33804427, 2021). "CD44 and CD133 are specific markers of primary colorectal CSCs associated with tumor growth, aggressiveness, and resistance in CRC." (PMID 34642302, 2021). "Dipeptidyl peptidase 4 (CD26)(+) CRCSCs enriched from CD133(+)/CD44(+) cells drive tumor metastasis." (PMID 33917482, 2021). "CD44, a transmembrane adhesion receptor for hyaluronan and growth factors, contributes to the migration and invasion by tumor cells." (PMID 34176441, 2021). "In adenocarcinoma, we detected platelets aggregates along the intestinal epithelium and a co-localization of CD44/P-selectin, thus indicating the strong presence of platelets in the tumor microenvironment and the platelets-intestinal cells crosstalk in cancer." (PMID 34439397, 2021). "Another study demonstrated that miR-141 suppressed tumour growth and metastasis of prostate CSCs by targeting the CD44 gene." (PMID 34944493, 2021). "Specific deletion of IFNAR in Tregs results in increased Treg proliferation and higher expression of PD-1 and CD44 on their cell surface, leading to decreased anti-tumor immune responses and tumor clearing in mouse models of colon cancer and melanoma." (PMID 33801234, 2021). "Nevertheless, this data should be complemented with the methylation state of the promoter of CD44 since there are instances where it is frequently hypermethylated and functions as a silencer of tumor progression." (PMID 33505471, 2021). "The expression of CD44 in ectopic tumor xenograft collected from the TNBC-bearing mice model was investigated by immunohistochemistry." (PMID 33672756, 2021). "GrB-EGFR/CD44-NGs induced nearly complete growth suppression of the tumor in xenografted tumor models in nude mice." (PMID 33981532, 2021). "Aldehyde dehydrogenase (ALDH) is another well-accepted cell-surface marker for BCSCs, and studies have reported that ALDH+ BCSCs manifest intensified colony formation, tumor initiation, and chemo-resistance than CD44+/CD24− BCSCs." (PMID 34831048, 2021). "Flow cytometry analysis of tumor samples further confirmed that SF at 50 mg/ml eliminated 99.76 ± 0.05% CD44+/CD24− cells, 92.80 ± 0.26% MDR1 and 78.57 ± 0.11% PDL-1 positive cells from the tumor stroma." (PMID 34873206, 2021). "Of note, a homogenous population of luminal tumour cells, sorted based on low levels of CD44(CD44low), can regenerate the tumour bulk that contains CD44high cells (constituting 10% of the tumour bulk)." (PMID 34298745, 2021). "Beyond being markers, CD133 and CD44 can activate the PI3K/Akt pathway to drive tumor-initiating cells." (PMID 34831139, 2021). "The NK cell activating ligand MICA/B showed higher expression in the MDA-MB-231 tumor tissue than in RT-R-MDA-MB-231 or CD24−/low/CD44+ tumor tissue." (PMID 34502547, 2021). "Negatively charged hyaluronic acid (HA) has good biocompatibility, is capable of self-assembly, and improves tumor cell targeting efficiency because of the high expression of CD44 in various tumor cells." (PMID 34668829, 2021). "Alterations in the CXCL12/CXCR7 axis can influence tumor cell invasion and adhesion processes in prostate cancer, increasing the expression of CD44, and niche factors like VEGF, which suggests a role for CXCR7 in the CSC niche." (PMID 33530455, 2021). "We also identified peptides from the cell adhesion molecule CD44 in all three biospecimens, with the highest number of CD44 peptides found in the tumor tissue." (PMID 33413078, 2021). "Numerous studies suggest an important role of CD44 protein in serum as a good biomarker of tumor burden and metastasis." (PMID 34599251, 2021).
tumor (continued). "(B and C) Kaplan–Meier analysis of the DFS (B) and OS (C) of all patients in the testing group after they were stratified into ≥19.5% of CD44-/CD24- (n = 100) vs. <19.5% of CD44-/CD24- tumor cells (n = 121)." (PMID 34318746, 2021). "The intensity of the fluorescent signals (Rh6G-EGCG and DX) at the tumor site significantly increased locally within 24.0 h, indicating continuous and sustained drug delivery by NPs targeting P-selectin and CD44 in the tumor." (PMID 34575403, 2021). "This group reported that just 100 CD44+CD24+ESA+ cells were sufficient to faithfully capture the full characteristics of the primary human tumour in an orthotopic mouse xenograft model." (PMID 33799834, 2021). "Compared with parental adherent cells, tumor spheroid cells showed increased expression of CD44, suggesting the stemness properties of tumor sphere cells." (PMID 33986804, 2021). "CD44 is a multifunctional transmembrane protein that mainly mediates tumor metastasis, as well as cell-cell interaction; various metastatic cancer cells exhibit increased expression of CD44 and its isoform." (PMID 34957091, 2021). "The CD44 interacted with HA in the tumor/normal junction of PDX tumor tissues was determined by FRET assay." (PMID 34770956, 2021). "MEDI5117 also displayed robust activity against trastuzumab-resistant HER2 tumor cells by targeting the CD44+/CD24- population." (PMID 34354950, 2021). "There were 11 DEGs associated with tumor cell differentiation and dedifferentiation between EGFP- CD44-/CD24- cells and EGFP+ CSCs and they included RHBDL2, HIST1H4H, DSCC1, ZNF710, ATP8B3, and others." (PMID 34318746, 2021). "Through bioinformatics software, it was found that the tumor stem cell markers CD44 and EpCAM promoter had MKL-1 binding site CArG box." (PMID 34239355, 2021). "Accumulating evidence demonstrates that CD44 suppresses cell adhesion and promotes tumor invasion and metastasis in various cancer types." (PMID 34441397, 2021). "For example, membrane-associated MT1-MMP, a key effector in invadopodia-dependent ECM degradation, interacts with CD44 in protrusions/invadopodia of ER- cells thus promoting proteolytic activities and tumor cell metastasis." (PMID 35111687, 2021). "The CD44+CD133+ subpopulation of primary tumor-derived cells was able to initiate tumor growth in vivo." (PMID 33994850, 2021). "Expression of the adhesion molecules E-cadherin and CD44 appear context-dependent, with switching within tumor emboli potentially playing an important role in tumor cell survival, during invasion and metastasis." (PMID 34069167, 2021). "Immunohistochemistry revealed that the tumor generated from the transplant of GDC40(GFP)CD44 expressed CD44 in almost all tumor cells, whereas CD34‐positive neovascularization was very low compared with the tumor from the transplant of GDC40(GFP)." (PMID 33543833, 2021). "CD44 is a transmembrane glycoprotein and primary receptor through which hyaluronan (HA) activates different intracellular pathways resulting in tumor cell growth, migration, invasion, and angiogenesis." (PMID 33917061, 2021). "For these reasons, CD44 is a promising target for cancer therapy, particularly for tumours overexpressing CD44." (PMID 34944493, 2021). "HA can promote tumor-associated macrophages to produce growth factors and ECM components through a CD44-dependent pathway." (PMID 33986244, 2021). "In conclusion, we demonstrated a therapeutic potential of tumor suppressive miR-138 through direct downregulation of CD44 for the treatment of primary GBM." (PMID 33911148, 2021). "BCSCs having CD44+/CD24− tumor-initiating and self-renewing capacities are primarily responsible for TNBC resistance and relapse." (PMID 33925129, 2021). "These authors suggested CD133+CD44/high tumor cells as a predictive biomarker of hematogenous metastasis, and a possible target for reducing HCC metastatization." (PMID 34572776, 2021).
tumor (continued). "Further, CD44 expression was shown to correlate with stem cell-like properties such as chemotherapy resistance, enhanced spheroid formation and tumor-initiating capacities." (PMID 33925297, 2021). "In various tumor cell lines and human tumors the extracellular portion of CD44 serves as a substrate for proteolytic cleavage processes by metalloproteinases (MMPs)." (PMID 34307351, 2021). "The same as OPN, hyaluronan (HA) is mainly an abundant ECM component, and the HA/CD44 axis plays a significant role in a number of biological functions, promoting tumor progression and therapeutic resistance, eventually resulting in poor prognosis." (PMID 35154001, 2021). "In vitro and in vivo experiments, including analysis of tumor spheroid formation, CD44+ sub-population with stemness, stemness marker expression, and tumor-initiating ability, were performed to evaluate the effects of miR-375 on the stemness of GC cells." (PMID 34090492, 2021). "Mechanism of its action include either to promote the creation of a capsule from the connective tissue, resulting in the encompassing of the tumor, proteolytical activation of CD44, or binding to the cell membrane of the tumor cells." (PMID 33532580, 2021). "An example is the recombinant monoclonal antibody RG7356 that blocks the binding of all CD44 isoforms to hyaluronic acid to reduce tumor growth in vivo by successfully phagocytizing CD44 + CSCs." (PMID 34503571, 2021). "CD44+ cells were also found to induce less INF-gamma expression in CD8+ tumor infiltrating lymphocytes (TILs) when co-cultured with these cells compared to the CD44− subgroups, suggesting lower immunogenicity of the CD44+ population." (PMID 35047489, 2021). "Dual targeting with magnetic targeting and CD44 active targeting of HeLa-tumors in mice resulted in highly specific uptake of the nanotheranostic agent at the tumor site, as imaged by MRI and NIRF." (PMID 33391494, 2021). "DDIT3 regulon is upregulated in CD44+ tumor cells, which can inhibit type I interferon (IFN-I) and IFN-stimulated gene production." (PMID 35187044, 2021). "As an adhesion molecule related to tumorigenesis and tumor metastasis, cluster of differentiation-44 (also known as CD44) is overexpressed in TNBC." (PMID 34011362, 2021). "A previous study demonstrated that high-MW HA (HMW-HA) binds CD44+ tumor cells, inhibiting proliferation." (PMID 34770956, 2021). "CD44 is a kind of glycoprotein overly expressed in a variety of mammalian tumor cells including prostate, breast, colon, gastric, head, and squamous cell carcinoma." (PMID 35431911, 2021). "The cancer cell surface marker CD44 promotes tumor invasion and metastasis by mediating crosstalk between cancer cells and the TME." (PMID 34404882, 2021). "The expression of CD44 has been elevated in many types of cancer, often localizing in tumor cells’ filopodia, suggesting its role in cellular motility; a prerequisite for cancer spreading." (PMID 33540535, 2021). "According to their work, CD44+/CD24low/− cells belong to the mesenchymal-like BCSCs, are primarily quiescent, highly invasive, and are localized at the tumor invasive front." (PMID 34315857, 2021). "CD25-targeted NIR-PIT with CD44-targeted NIR-PIT resulted in a substantial complete response rate in CD44 overexpressing tumour models." (PMID 34332294, 2021). "Cell uptake experiments confirmed that the specific binding of HA and CD44 achieved specific targeting effect on tumor cells." (PMID 33792436, 2021). "Tumor-dissociated cells, examined for the presence of stemness marker CD44+/CD24-, showed higher stemness in vehicle-treated group (87.6%) compared to triple-therapy-treated tumors (48.6% for DGD and 65.2% in CGD)." (PMID 34889737, 2021).
tumor (continued). "In vivo studies have demonstrated that HA functionalized nanoparticles target CD44 over-expressing tumor sites, and exhibit enhanced stability in the bloodstream." (PMID 34439185, 2021). "HA can actively target solid tumors overexpressing CD44, while disulfide bonds can selectively release the drug in tumor sites with high glutathione expression." (PMID 35053199, 2021). "Cytofluorimetric analysis of Sca1+ and CD44+/CD24− was performed in the primary tumours explanted from BALB-neuT mice or from BALB/c mice s.c. injected with TUBO, 4T1 or TS/A cells." (PMID 33257841, 2021). "Previous research suggests that the Spp1:Cd44 signalling axis acts as an immune checkpoint thus, inducing host tolerance during tumour formation." (PMID 33686070, 2021). "Despite its physiological role, CD44 is widely and highly expressed in several neoplasms and it participates in cancer cell proliferation, migration, and invasion." (PMID 34833068, 2021). "Cluster of differentiation 44 (CD44), an adhesive molecule, is important for attachment of tumor cells to the peritoneum." (PMID 34268118, 2021). "CD44 has various biological functions, including leukocyte homing, wound healing, cell proliferation and migration, as well as tumour cell growth, invasion and metastasis." (PMID 33210459, 2021). "Activation of CD44 influenced tumor cell metabolism by inducing Hypoxia-inducible factor 1α (HIF1α) binding to nuclear DNA to increase glycolysis, in turn, rendering a metabolic shift in cancer cells." (PMID 33540535, 2021). "The use of CD44 as a tumour target is a well-known marker of cancer stem cells as it is expressed on the cell membrane of several cancers." (PMID 34200194, 2021). "HA was used to target delivery because of the specific binding ability of HA to CD44 molecules, which are overexpressed in a variety of tumor tissues." (PMID 34198550, 2021). "(B) Representative plots (left) and statistical analysis (mean ± SEM) of gated CD44+ CD4+ tumor-infiltrating lymphocytes (TILs) analyzed for puromycin incorporation." (PMID 34787568, 2021). "Micro positron emission tomography (micro-PET) and Fluorescence imaging showed an accumulation of the MLPs in the tumor tissue and uptake by cells overexpressing CD44+ marker in an MDA-MB-231 xenograft mouse tumor model." (PMID 34361141, 2021). "More specifically, in vitro cells only exhibited a small subfraction of CD44+ tumor cells (dot plot)." (PMID 34070094, 2021). "CSCs are thought to represent a minor sub-population in most cancers and, indeed, CD44+ CSCs are believed to constitute some 10% of the tumour cell population." (PMID 34831291, 2021). "Better understanding of CD44+CD133+ tumor-initiating cells will help to overcome this problem and improve therapeutic strategies." (PMID 33994850, 2021). "A previous study revealed that the tumor-associated macrophages interacted with CD44+ cancer stem cells and enhanced tumorigenesis via the OPN/CD44 axis." (PMID 34685653, 2021). "CD44 is involved in regulating a variety of biological behaviors, especially cell-cell interactions, stemness, and tumor metastasis and progression." (PMID 33819194, 2021). "Aberrant expression and/or dysregulation of CD44 facilitate tumor formation in multiple organs, including lungs, ovaries, liver, glioma, and thyroid gland." (PMID 34684168, 2021). "CD133 and CD44 stem cell markers were also expressed in gliomaspheres derived from recurrent GBM tumours." (PMID 34066147, 2021). "Collectively, our data demonstrate that orthotopic PCa tumour-derived ALDH+CD44+CXCR4+CD24+ cell compartment is a maintainable subpopulation of pluripotent PCSCs with more tumorigenic and metastatic potential than other isogenic PCa cells." (PMID 34247196, 2021). "The purpose of this study is to investigate the expression of CD44 in tumor tissues as well as serum of SCLC patients and explore its correlation with the clinical characteristics, therapeutic effect and prognosis." (PMID 34187156, 2021).